CD38 (CD38 molecule)
Diseases named in the same sentence as CD38 in open-access papers (continued):
Sharing a sentence is not in itself a finding about the gene and the disease.
COVID-19 (continued). "In summary, the expression of activation markers (CD69, HLA-DR, CD38) on T cells was closely linked to the co-expression of inhibitory receptors (PD1, LAG-3, TIM-3) on T cells in COVID-19 and malaria patients." (PMID 32983106, 2020). "We found that T-cell activation appears to correlate with disease severity in COVID-19 patients as a higher frequency of activated CD8+ T cells (defined by CD38+ and HLA-DR+) occurred in severe patients with longer time after disease onset." (PMID 32641700, 2020). "For example, for CD8 T cells, the region of the tSNE map containing KI67+ and CD38+HLA-DR+ CD8 T cell populations that was enriched in COVID-19 patients at D0 was preserved at D7." (PMID 32669297, 2020). "The first report of the immune dynamics during mild COVID-19 demonstrated that in a single patient the number of circulating CD8+ T-cells (CD38+ HLA-DR+) and antibody secreting B cells increased early in disease, peaking 8 to 9 days after symptom onset." (PMID 33302366, 2020). "Of note, CD8+ CM, TM, and EM T cells showed particularly high frequencies of HLA-DR+CD38+ cells in COVID-19 and patients infected with P. falciparum." (PMID 32983106, 2020). "The proportion of CD38+PD-1+CD8+ T cells was significantly higher in the fatal cases of COVID-19 than those found in the survivors 3 weeks later (P <0.05 for all)." (PMID 33362779, 2020). "To discern whether the expansion of CD38+HLA-DR+ T cells is specific to COVID-19 or a general consequence of infection, we extended our investigation to encompass a larger cohort." (PMID 40370439, 2025). "Overall, these results indicated the prognostic potential of the CD38+HLA-DR+ T subset in COVID-19." (PMID 40370439, 2025). "We revealed a significant increase in CD38+HLA-DR+ T cells in non-survivor COVID-19 patients, establishing them as an independent risk factor for 28-day mortality." (PMID 40370439, 2025). "Our study reveals a significant increase in CD38+HLA-DR+ T cells in severe COVID-19 patients." (PMID 40370439, 2025). "The survivors’ proportion of CD8+CD38+ cells declined subsequent to their recovery from COVID-19." (PMID 38474367, 2024). "Therefore, in this study, we investigated and assessed the expression of CD27 and CD38 proteins on B cells to identify any changes in the circulating B cell subset in patients with severe COVID-19." (PMID 39407725, 2024). "Here, T-cell receptor (TCR) RNA sequencing was performed on HLA-DR+/CD38+CD8+ T-cell subsets of hospitalized coronavirus disease 2019 (COVID-19) patients (n = 30) and healthy controls (n = 30; 10 of whom had previously been exposed to severe acute respiratory syndrome coronavirus 2 [SARS-CoV-2])." (PMID 37787611, 2024). "Accumulation of Cd38+ macrophages may indicate the severe pneumonia at d5, as CD38 has been reported to be an inflammatory marker of human monocytes and macrophages and involved in COVID-19 pathophysiology." (PMID 39414783, 2024). "Finally, NK cells cocultured with monocytes from both moderate and severe COVID-19 patients had a higher proportion of activated (CD38+ CD69+) cells." (PMID 38578283, 2024). "As a marker of this population, CD38 may be a key regulator of T-cell depletion in COVID-19 patients." (PMID 39852780, 2024). "Moreover, an increased frequency of activated CD8+ T cells was observed in COVID-19 convalescent patients, both in CD38+ human leukocyte antigen-DR (HLA-DR)+ cells and CD56+ cells (P = 0.036)." (PMID 37824612, 2023). "Activated CX3CR1+ CD8+ T cells and activated HLA-DR+ CD38+ or Ki67+ CD8+ and CD4+ T cells are found to be more abundant in MIS-C than in patients with severe pediatric COVID-19, but HLA-DR+CD38+ CD8+ T cells frequencies decreased in the first two weeks of admission in MIS-C." (PMID 36982783, 2023).
COVID-19 (continued). "Indeed, when we compared the phenotype of ILC2 present in the PBMC of HC and COVID-19 patients, we found that COVID-19 patients’ ILC2 showed a more activated phenotype characterized by an increase in CD38 and CD69 expression and a trend for increased NKG2D." (PMID 37207201, 2023). "Indeed, CD38 is highly up-regulated in T lymphocytes of COVID-19 acute patients, and decreases over time once the infection is resolved and the inflammation state disappears." (PMID 36941056, 2023). "In previous studies involving COVID-19 patients, an overactivation of the immune system by HLA-DR+CD38+ T cells was found, even 12 months after infection, probably due to both the initial lymphopenia and the role these cells play in providing help to B lymphocytes." (PMID 38035104, 2023). "Increased CD38 expression in severe COVID-19 CD8+TM was closely clustered with exhaustion-coding genes (LAG-3, TIGIT) suggesting CD38 expression is associated with metabolic reprograming, memory impairment, and cellular exhaustion of CD8+TM in the lung of COVID(+) patients." (PMID 37029220, 2023). "There was a significant correlation between worst COVID-19 outcome on the 8-point scale and activated cTfh cells (P = 0.005) and between worst COVID-19 outcome on the 8-point scale and both CD38 and HLA-DR upregulation on CD4+ T cells (P = 0.008) and CD8+ T cells (P = 0.002)." (PMID 36862515, 2023). "With a view to the various effects of CD38 on the functions of immune cells, the use of CD38-targeted therapies may be a viable treatment option for those life-threatening COVID-19 patients." (PMID 37165408, 2023). "In terms of abundance, CD38+KLRG1−CD8+ T cells (both ‘antigen’ and ‘antigen_prolif’ clusters), but not the CD38+KLRG1+CD8+ T cell clusters, were associated with the severity and trajectory of COVID-19." (PMID 37735591, 2023). "Concerning COVID-19 T8 lymphocytes, we noticed a differentiation (decrease in naïve and central memory cells contrasting with an increase in effector memory cells), activation (CD38+, CD38hi, and HLA-DR+CD38+), and exhaustion (PD-1+)." (PMID 38235145, 2023). "Therefore, the dysregulation of CD38 in COVID-19 can have a role in the control of infection and immunopathogenesis." (PMID 36405703, 2022). "Both of them showed increased CD38+ expression in HD patients already with mild/asymptomatic COVID-19 and even more with moderate/severe COVID-19, thus providing an effective response to the viral infection and thereby being one explanation for the improved outcome in this cohort." (PMID 35265078, 2022). "At the same time, recent studies have found that S-specific memory B-cells with the IgD–CD21+CD27+CD38–CD71int/- phenotype are detected in patients who recovered from severe COVID-19 six months ago, suggesting that effective immunity can be induced even in this group of patients." (PMID 35632823, 2022). "HD patients might be protected from severe COVID-19 due to their chronic inflammatory state with increased CD38+CD8+ effector memory and TEMRA T cells as well as CD161+CD8+ T cells." (PMID 35265078, 2022). "In addition, individuals recovered from critical COVID-19 had elevated levels of activated (defined as CD38+HLA-DR+) CD8+ effector and terminal memory T cells (Bonferroni-adjusted P-value range 5.46 × 10−4–1.04 × 10−6)." (PMID 36433939, 2022). "Furthermore, CD38+HLA-DR+ CD4+ T cells were detected at high frequency in COVID-19 respiratory samples than in blood samples." (PMID 35898494, 2022). "The anti-CD38 therapy results indicated a depletion of antibody-producing plasma cells and was associated with a weak or non-existent response to COVID-19 vaccines in previous trials." (PMID 36428605, 2022). "Therefore, it is conceivable that acute NAD+ depletion upon SARS-CoV-2 infection contributes to inefficient CD38-dependent OT secretion, inducing smell and taste perception disturbances in COVID-19 patients." (PMID 35457123, 2022).
COVID-19 (continued). "Notably, the CD21 low CD38 low B cell number was moderately increased in severe and critical COVID-19 patients than those in mild cases." (PMID 36403042, 2022). "Additionally, it is worth noting that activated CD38+HLA-DR+CD8+ T cells from acute COVID-19 patients contained higher levels of intracellular granzyme A and B along with perforin proteins vs. convalescent COVID-19 patients or control subjects." (PMID 36146713, 2022). "Moreover, patients with severe COVID-19 had higher counts of circulating activated CD38+HLADR+ and ‘exhausted’ CD27−CD28− CD8 phenotype cells compared to the mild severity group." (PMID 35632823, 2022). "The frequency of CD38+ NK cells was similar in COVID-19 and influenza patients." (PMID 35371005, 2022). "In addition, more cells expressing Ki-67 and activation antigens CD38 and HLA-DR were detected among the total circulating Tfh cells of patients with COVID-19 than in the control group." (PMID 35632823, 2022). "Additionally, patients treated anti-B cell antibodies targeting CD20 or CD38 antigens as part of their standard of care had significantly lower antibody responses after COVID-19 vaccination." (PMID 34804957, 2021). "However, lower percentages of ICOS-1+CD8+ T, ICOS-1+CD4+ T, and CD38+CD4+ T cells were observed in severe COVID-19 patients." (PMID 33692788, 2021). "Results of univariate and multivariate logistic regression in our study indicate, that expression of CD38 on CD8+ cells alone or together with expression of PD-1 on CD4+ cells could be used as a biomarker of survival in hospitalized patients with COVID-19." (PMID 33937096, 2021). "Similarly, CD38+HLA-DR+cTfh cells, activated CD4+T cells and cytotoxic CD8+T cells were expanded in COVID-19 patients, and increased CD38+HLA-DR+cTfh cells indicated a recent antigen encounter and emigration from the GC of the patients." (PMID 34603308, 2021). "We next determined the activation status of CD4+ and CD8+ T cells and observed that patients with moderate and severe COVID-19 show increased accumulation of activated HLA-DR+CD38+CD8+ T cells, which distinguished these cohorts from healthy controls and convalescent individuals." (PMID 34745145, 2021). "In particular, CD38 was found to distinguish COVID-19 patients at the RNA level; thus, it may serve as a potential host target for antiviral research." (PMID 34899651, 2021). "Importantly, the functionality of memory CD8 + T cells and CD8+ PD-1+ CD38+ T cells in severe COVID-19 patients was demonstrated by high expression levels of perforin and granzyme B compared to normal lymphocytes." (PMID 34359987, 2021). "It seemed, therefore, that low levels of CD4+ CD38+ cells in COVID-19(+) patients could distinguish these patients from other inflammatory diseases." (PMID 33419040, 2021). "Moreover, patients with COVID-19 showed much higher frequency of CD38+HLA-DR+ CD8+ T cells than healthy controls (1.47% ± 0.50%; n = 5)." (PMID 32627758, 2020). "Similar to previous research on the Ebola and influenza viruses, the frequency of CD38+HLA-DR+ CD8+ T cells was found to have promptly increased in patients with COVID-19 from day 7 (3.57%) to day 8 (5.32%) and day 9 (11.8%) and then decreased at day 20 (7.05%)." (PMID 32627758, 2020). "Furthermore, CD38 may act as an NADase and contribute to the generation of pathological CD38+HLA-DR+ T cells in the context of COVID-19." (PMID 40370439, 2025). "Previous treatment with an anti-CD20 monoclonal antibody was associated with higher rates of COVID-19, while previous treatment with anti-CD38 monoclonal antibody was not, as was the case for recipients of hematopoietic stem cell transplantation or CAR-T cell therapy." (PMID 38092996, 2024). "Moreover, the role of NAD+ metabolism by the enzyme CD38 has been suggested in COVID-19." (PMID 37158917, 2023). "However, higher or lower expression of CD38 in HLA-DR+ T cells may promote different functions in co-activated T cells from severe COVID-19 patients." (PMID 38035104, 2023).
COVID-19 (continued). "Thus, targeting CD38 enzymatic activities may contribute to designing novel therapeutics which would help alleviate the detrimental COVID-19 effects." (PMID 36675642, 2023). "Similar to our findings in NK cells, the proportion of activated HLA-DR+CD38+ γδ T cells was higher in healthy pregnant women compared with nonpregnant women (mean 4.4% and 0.8%, respectively), but became similar during acute COVID-19 (mean 4.0% and 6.1%, respectively)." (PMID 37036008, 2023). "Nevertheless, irrespective of including healthy and follow-up samples in the PCA, CD38+Ki67+ Tregs as well as cTfr and plasma cells/blasts were among the top 10 loadings for principal component 1, thus confirming these subsets as important contributors to COVID-19 immunobiology." (PMID 36669118, 2023). "Furthermore, a decreased proportion of naïve IgD+CD38– B cells noted in patients with COVID-19 may point to altered bone marrow B cell differentiation." (PMID 35337053, 2022). "Moreover, similar results were observed in COVID-19 non-survivors, and increased expression of PD-1 combined with increased expression of CD38 on CD3+CD8+ T cells was shown to be a risk factor for unfavourable outcomes in patients with COVID-19." (PMID 35741107, 2022). "Thus, a distinct ratio of these two subsets might contribute to different immune response and clinical outcome of HLA-DR+CD38+ CD8+ T cells in COVID-19 progression." (PMID 34567001, 2021). "Regarding circulating effector B cells, it was found that COVID-19 patients had upregulated level of Ki67 marker as well as surface activation marker CD95 in circulating CD27+CD38+CD138+ B cells that might suggest about recent emigration from germinal center of the secondary lymphoid tissues." (PMID 35723393, 2021). "Compared with the survivors, our data showed that the fatal cases of COVID-19 exhibited high and persistent expression of CD38+HLA-DR+ and CD38+PD-1+on CD8+ T cells as well as high levels of SARS-CoV-2 throat viral load, which may be indicative of prolonged virus exposure in the fatal cases." (PMID 33362779, 2020). "Studies have noted increased CD38+HLA-DR+CD8+ T cells in H7N9 influenza and COVID-19, particularly in critically ill cases, suggesting their prognostic value and involvement in severe immune dysregulation." (PMID 40370439, 2025). "Both CD4+ and CD8+ Ki-67+ cells, along with hyperactivated (HLA-DR+CD38+) CD4+ T cells, showed significant increase, and CD4+ PD-1+ showed an increasing trend in COVID-19+ with culture." (PMID 40698364, 2025). "Regardless of the disease outcome, decreased frequency of CD28+, CD38+, and CD62L− CD4+ T-cell subsets were observed in both COVID-19 subgroups." (PMID 39597661, 2024). "Later at D14–28, 16 cell subsets presented elevated global accuracy (AUC ≥ 0.8) to classify COVID-19 vs. HCs, with AUC = 1.0 registered for CD4+CD38+ and CD8+CD69+ and AUC = 0.9 observed for CD8+CD27+, CD3+CD107a+, CD4+T-bet+, CD8+CD107a+ and CD3+CD38+." (PMID 39597661, 2024). "A significant expression of vimentin and infiltration of immune cells (CD68+, CD38+, and CD138+) in the testicular tissue of COVID-19 cases, along with extensive immunoglobulin G precipitation and reduced inhibin expression (p = 0.001) were observed." (PMID 39866583, 2024). "The results demonstrated that, at D0, nine cell subsets presented robust global accuracy (AUC ≥ 0.8) to classify COVID-19 vs. HCs, with outstanding performance (AUC = 0.9) observed for CD8+CD69+, CD4+CD38+, CD3+CD38+ and CD8+CD27+." (PMID 39597661, 2024). "Overall, our findings demonstrated that, regardless of the time points along the timeline kinetics, CD4+CD38+ and CD8+CD69+ presented outstanding accuracy (AUC ≥ 0.9) in classifying COVID-19 patients vs. HCs." (PMID 39597661, 2024). "The CD4+CD38+ and CD8+CD69+ subsets accurately classified COVID-19 vs. healthy controls throughout the kinetic analysis." (PMID 39597661, 2024).
COVID-19 (continued). "Our review delves into the significance of NAD+ metabolism in COVID-19 pathology, marked by decreased NAD+ levels and upregulated NAD+-consuming enzymes such as CD38 and poly (ADP-ribose) polymerases (PARPs)." (PMID 39852780, 2024). "Prior findings reported that, in COVID-19, especially in severe patients, activation and exhaustion markers on the T cell surface were upregulated during acute infection, such as CD69, OX40, CD38, 4-1BB, PD-1, CTLA-4, LAG-3, TIM-3, and TIGIT." (PMID 39355257, 2024). "Of the COVID-19 patient group’s (n = 30) CD3+ cell fractions, on average, 24.4 ± 11% were CD8+ T cells, of which 10.7 ± 7.3% were HLA-DR+CD38+." (PMID 37787611, 2024). "An increase in CD19+, CD19+CD38+IgMlow, CD19+CD38+CD27highIgMhigh, and CD19+CD81+ lymphocytes and decrease in the lymphocyte count and NK cell percentage were correlated with severity in COVID-19-infected children." (PMID 38813014, 2023). "Correlation analysis of the CD38 and HLA-DR expression levels revealed a positive correlation between these receptors in CD56− T cells obtained from ICU and moderate severity COVID-19 patients." (PMID 37240393, 2023). "We demonstrate that the tetravalent S1 subunit protein COVID-19 vaccine candidate induces CD4+ and CD8+ T cell activation, as indicated by increased expression of CD69, HLA-DR, CD38, and Ki-67 activation and proliferation markers on both T cell subsets." (PMID 37830800, 2023). "The relationship between the activation of CD38 and depletion of NAD+ was highlighted as an aging-related feature with an evident role as a COVID-19 modulator in the elderly." (PMID 36675642, 2023). "Such analysis carried out in this study, has shown that the percentage of both CD38+ HLA-DR+ CD4+ and CD8+ T cell subpopulations is significantly higher in the peripheral blood of COVID-19 patients, compared to HS and VS control groups." (PMID 35898494, 2022). "By performing an unbiased analysis of respective markers and populations, we detected a significant increase in CD38+CD8+ effector memory and TEMRA T cells only in HD patients depending on their COVID-19 severity." (PMID 35265078, 2022). "Previous studies reported that CD38, HLA-DR, and Ki-67 significantly upregulated in CD8+ T cells from patients with severe COVID-19, indicating T cells' activated phenotype." (PMID 35655192, 2022). "We found a significant increase in the expression of CD38 and CD69 in the active COVID-19 patients compared to the healthy and recovered, suggesting an activated T cell response." (PMID 36532041, 2022). "We found higher frequencies of neutrophils, intermediate CD14+CD16+monocytes, activated HLA-DR+CD38+ CD4+ T cells, EM-like CD4+ and CD8+ T cells in COVID-19 respiratory compared to blood samples." (PMID 35589689, 2022). "We also observed that the subpopulation of CD38++CD27 transitional B cells was decreased, while mature activated B cells (CD27+CD38+) and resting memory B cells (CD27+CD38−) frequencies increased in most subjects from both groups of COVID-19 patients." (PMID 35807783, 2022). "An increase in the percentage of CD38+ and HLA-DR+ memory CD4+ and CD8+ T cells was also detected in severe COVID-19 patients compared to healthy subjects in other recent studies and this correlated with poor prognosis." (PMID 35898494, 2022). "The concept of T cell activation has been widely described by the abundance of CD38+, HLA-DR+ and Ki67+ CD8+T cells in COVID-19 patients." (PMID 35284964, 2022). "In support of our findings, lymphocyte activation markers such as CD38, CD69, and CD44 are highly expressed on CD4+ and CD8+ T cells of COVID-19 patients, and CD73 absence in CD8+ T cells induces granzyme production in these individuals." (PMID 36248842, 2022). "In the acute phase of COVID-19, SARS-CoV-2-specific CD8+ T cells expressed activation markers (CD38 and HLA-DR) and secreted cytotoxic molecules (perforins and granzyme B), indicating these cells were activated with cytotoxic functions." (PMID 36505489, 2022).